TBX1 (T-box transcription factor 1)
Diseases named in the same sentence as TBX1 in open-access papers (continued):
Sharing a sentence is not in itself a finding about the gene and the disease.
tumor (26 papers, 2009 to 2025). "TBX1 was highly expressed in PCa tissues, and high TBX1 expression was positively associated with Gleason score, pathological tumor stage, pathological lymph node stage, extraprostatic extension and disease/progression-free survival." (PMID 33575219, 2020). "High expression of TBX1 in PCa is positively correlated with poor tumor pathological staging, poor pathological lymph node staging, and short progression-free survival." (PMID 38965548, 2024). "Of note, the median expression value of TBX1 was greatest in the KRT14+ high TM group compared to the other 32 TCGA pan‐cancer tumor types." (PMID 39258580, 2024). "To identify potential TFs contributing to TBX1 expression in CML tumor cells, we screened TF binding sites given by the UCSC genome browser." (PMID 38203204, 2023). "CDKN1A showed low expression levels in TBX1-positive K-562 and TK-6 cells, supporting its tumor suppressor status in this disease." (PMID 38203204, 2023). "To examine the role of TBX1 in epithelial carcinoma, we first investigated TBX1 expression in carcinoma using human tumor bulk RNA-sequencing data from different origins." (PMID 36418889, 2022). "In summary, we demonstrated that TBX1 played an anti-tumor role in CC cells and enhanced the chemosensitivity of CC cells to cisplatin." (PMID 33557670, 2021). "Taken together, although the specific role of TBX1 varied in different types of tumor, its anti-tumor effect on CC progression was strongly supported." (PMID 33557670, 2021). "In a subsequent experiment, in vivo experiments need to be performed to further confirm the inhibitory effect of TBX1 on CC tumor development and metastasis." (PMID 33557670, 2021). "In the present study, we confirmed that TBX1 was targeted and down-regulated by miR-6727-5p in CC cells, and the silence of TBX1 reversed the anti-tumor effects of the miR-6727-5p inhibitor on CC cells." (PMID 33557670, 2021). "In the same study, it has been shown that TBX1 expression in tumor cells significantly decreases cell growth and colony formation." (PMID 30209892, 2018). "Specifically, amplified TBX2 in BC might acts as a mediator of cell senescence and thus promotes tumor progression via repressing tumor suppressors such as p16 or p21 in cell cycle (TBX1)." (PMID 37860520, 2023). "In the present study, we hypothesized that TBX1 played an anti-tumor role in CC and was targeted by miR-6727-5p." (PMID 33557670, 2021). "This study demonstrates that TBX1, a target gene of miR-6727-5p, acts as a tumor suppressor in CC, indicating that TBX1 may be a new target for CC therapy." (PMID 33557670, 2021). "T-box transcription factor 1 (TBX1), a member of the T-box family, has anti-tumor effects in some types of cancer, but its role in CC is yet unknown." (PMID 33557670, 2021). "Emerging studies have reported the function of TBX1 in tumor progress." (PMID 33557670, 2021). "In summary, TBX1 expression identifies heterogeneity between and within tumor samples." (PMID 31963474, 2020). "In this study, our data provide strong evidence supporting the tumor-promoting role of TBX1 in PCa." (PMID 33575219, 2020). "Notably, the most complex patterns of amplifications or deletions were identified as 22q11.21 region in HN30, HN31, and HN12, and this region comprises TBX1 that also involved negative regulator of tumor cell growth." (PMID 27501229, 2016). "However, whether TBX1 promotes tumor progression by increasing the enrichment of H3K4me1 as well as UBF on rRNA genes is still unclear, and further studies are needed to elucidate these specific mechanisms." (PMID 38965548, 2024). "In addition, TBX1 silencing reduces enrichment of the rRNA genes H3K4me1 and Upstream Binding Factor (UBF) (key transcriptional regulators of rRNA synthesis) and inhibits PCa progression, suggesting that TBX1 may affects tumor progression in this epigenetic manner." (PMID 38965548, 2024).
tumor (continued). "To evaluate browning of perirenal AT, we measured mRNA levels of Prdm16, TBX1, Ucp1 and PGC1 alpha in AT from normal and tumor kidney." (PMID 35606546, 2022). "Further differential and pathway analysis revealed remodeling of endothelial cells in AML, including high expression of C-C Motif Chemokine Ligand 21 (CCL21), TBX1 and NRP2 specifically observed in tumor LECs." (PMID 36028490, 2022). "We examined the effect of TBX1 silencing on the growth of implanted DU145 cells tumors in vivo and found significant decreases in the tumor volumes and weights of TBX1-silenced cells compared with those in control cells." (PMID 33575219, 2020). "Regulatory mechanisms of TBX1 and the expression of ZEB1 and ZEB2 may differ among tumor types, organs, or species; however, the complete molecular mechanism underlying this effect is unknown." (PMID 36418889, 2022).
cancer (11 papers, 2020 to 2024). A tumor composed of atypical neoplastic, often pleomorphic cells that invade other tissues. "Here, we explored genome-wide gene expression and chromatin remodeling in two independent cellular models of Tbx1 loss of function, mouse embryonic carcinoma cells P19Cl6, and mouse embryonic stem cells (mESCs)." (PMID 33015063, 2020). "TBX1 is thought to suppress cancer cell growth in mouse skin tumors." (PMID 38965548, 2024). "TBX1 was a prognostic marker of multidrug resistance and cancer progression." (PMID 36545327, 2022). "Besides, emerging studies have shown that TBX1 is a double-edged sword in the development of cancers." (PMID 33557670, 2021). "The distribution of TBX1+ cells within the cancer lesion was variable." (PMID 31963474, 2020). "TBX1 overexpression may participate in tumorigenesis and cancer progression and be a potential molecular marker of PCa." (PMID 33575219, 2020). "Additionally, aberrant expression of TBX1 has been detected in multiple types of cancer." (PMID 33557670, 2021). "Therefore, the role of TBX1 in cancer may be tissue specific or cell-type dependent." (PMID 33575219, 2020). "Further research will be necessary to establish whether in this context Tbx1, might trigger an autoregulatory loop (Tbx1-WNT-Sox9-Tbx1) that reduces the dependence of BCC cancer cells from SHH signaling." (PMID 31963474, 2020).
psychiatric disorder (4 papers, 2005 to 2021). A disorder characterized by behavioral and/or psychological abnormalities, often accompanied by physical symptoms. "Several genes encoded in the 1.5-Mb region (e.g., Tbx1, Dgcr8, Comt, Sept5, and Prodh) have been identified as potentially associated with psychiatric disorder-like behavioral phenotypes." (PMID 33845872, 2021). "In fact, some genes within the 1.5-Mb region (e.g., Tbx1, Dgcr8, Prodh, and Sept5) have been identified as potentially associated with phenotypes relevant to psychiatric disorders by animal model studies." (PMID 32066675, 2020).
neurodevelopmental disorder (3 papers, 2022 to 2024). A behavioral and cognitive disorder with onset during the developmental period that involves impaired or aberrant development of intellectual, motor, or social functions. "In addition, although human studies have reported an association between loss-of-function TBX1 variants and neurodevelopmental disorders, their effects on cognitive function remain uncharacterized." (PMID 34737458, 2022). "While analysis of 22q11.2 hemizygous carriers or its mouse models does not pinpoint the impacts of single genes, there are ultrarare cases of TBX1 variants without 22q11.2 deletions with neurodevelopmental disorders." (PMID 37461714, 2023).
cardiac disease (2 papers, 2018 to 2021). "CTD, the common type of cyanotic cardiac disease, is usually defined as malformations of the OFT, and TBX1 participates in OFT development." (PMID 34332615, 2021).
infection (2 papers, 2014 to 2021). The state of being infected such as from the introduction of a foreign agent such as serum, vaccine, antigenic substance or organism. "The five TBX1 mutation positive subjects in groups 1+2 lacked cardiovascular lesion and manifested borderline to mild developmental retardation (while they had no susceptibility to infection, assessment of thymic hypoplasia remained fragmentary)." (PMID 24637876, 2014).
cardiovascular disease (1 paper, 2023). "Moreover, we included the T-box transcription factor gene tbx1 as a positive control, owing to its previous syndromic cardiovascular disease associations." (PMID 37584388, 2023).
lip (1 paper, 2020). "According to previous reports, TBX1 is considered to be responsible for cleft lip/palate phenotypes in both 22q11 deletion and 22q11 duplication." (PMID 32863884, 2020).
neurological disease (1 paper, 2025). "In one individual, the deletions spared both TBX1 and DGCR8, whose haploinsufficiency has been linked, respectively, with cardiac and neurological disease manifestations." (PMID 41368632, 2025).
TBX1 also shares sentences with these, for which no sentence is quoted: genetic disorder (6 papers); Williams-Beuren syndrome (5); immune dysfunction (3); microcephaly (3); pulmonary stenosis (3); Asperger syndrome (2); atrial septal defect (2); immunodeficiencies (2); mandible hypoplasia (2); Marfan syndrome (2); squamous cell carcinoma (2); 22q11.2 microduplication syndrome (1); 3MC syndrome (1); adolescent idiopathic scoliosis (1); Alagille syndrome (1); Angelman syndrome (1); ataxia telangiectasia (1); behavioral disorders (1); bladder cancer (1); Brugada syndrome (1); campomelic dysplasia (1); Cantu syndrome (1); carcinosarcoma (1); cerebellar ataxia (1); Char syndrome (1); Charcot-Marie-Tooth disease (1); Charcot-Marie-Tooth disease type 1A (1); chordoma (1); cognitive deficits (1); Combined immunodeficiencies (1).
A further 79 diseases each share a sentence with TBX1 in 1 paper.